HOXA2 (homeobox A2)
Diseases named in the same sentence as HOXA2 in open-access papers (continued):
Sharing a sentence is not in itself a finding about the gene and the disease.
cancer (14 papers, 2019 to 2026). A tumor composed of atypical neoplastic, often pleomorphic cells that invade other tissues. "The identification of hypermethylation of the HOXA2 gene as a biomarker for CRC in our study adds to the evidence of HOXA2′s association with cancer." (PMID 35054365, 2022). "Members of the HOXA2 gene family have also been implicated in the development of various cancers." (PMID 41415292, 2025). "Conversely, transgenic HOXA2 overexpression suppressed these cellular processes and promoted apoptosis of cancer cells." (PMID 39833374, 2025). "In 2019, Li and colleagues established a link between HOXA2 and age, cancer staging, lymphovascular invasion, and lymph node involvement in CRC." (PMID 35054365, 2022). "Through VENN analysis, we detected 603 upregulated and 1043 downregulated DEGs overlapping in the three cancer cell lines, including 16 upregulated TFs (e.g., HOXA2, HOXB2, HOXC10, and NKX2-1) and 36 downregulated TFs (e.g., BACH1 and CDX1), respectively." (PMID 32156290, 2020). "The relationship of HOXA2 with cancer progression is limited, and the role of HOXA2 in cancer prognosis and response to treatment is unknown." (PMID 35054365, 2022). "Two of our DVRs and a DMR for lymphatic–hematopoietic cancers were annotated to genes HOXA2 and HOXA-AS3 and overlapped with promoters of the HOX family, whose aberrant expression levels have been related to several cancers." (PMID 33632303, 2021). "We found that the methylation percentages of HOXA5, HOXA2, and HOXA6 in CRC tissue were up to 67.62, 58.36, and 31.32%, respectively, and ranked first in CRC among all cancer types analyzed." (PMID 31165042, 2019). "Genes involved in angiogenesis (HOXA2, HOXC5), genome instability (HOXC5, HOXC11), deregulating cellular energetics (HOXA4, HOXC5), and metastasis (HOXA2) were all up-regulated in ecDNA(+) cancers." (PMID 38896472, 2024). "The DNA methylation profiles of the 3 HOXA gene promoter regions were downloaded from TCGA, and the results demonstrated that the methylation levels of HOXA5, HOXA2, and HOXA6 were significantly elevated in cancer tissues compared with normal tissues (p < 0.0001)." (PMID 31165042, 2019).
tumor (12 papers, 2013 to 2025). "In summary, our study identifies HOXA2 as a novel prognosis-relevant tumor suppressor in the mammary gland." (PMID 39833374, 2025). "Suppression of HOXA2 expression significantly heightened cell proliferation, migration, and invasion in BC cells, and promoted tumor growth in mice." (PMID 39833374, 2025). "In three of the four cases, the HOXA2 promoter hybridization signal in NPC tumors was stronger than that in the non-tumor counterparts, indicating the amount of methylated HOXA2 DNA was comparatively higher in tumors." (PMID 24243817, 2013). "The methylation percentage of the same HOXA2 region was high in five clinical tumor samples (66.8~81%, average 74%) compared with their adjacent normal tissues (6.8~50.5%, average 25%)." (PMID 24243817, 2013). "Results showed that HOXA2 is highly expressed in tumor tissues compared to normal tissues." (PMID 38311789, 2024). "However, a study investigating HOXA2 revealed lower expression of the HOXA2 gene in GC tumor samples than in normal samples." (PMID 38311789, 2024). "Analysis of bulk expression data from both tumor cohorts identified high variance in expression levels of several H3K27me3-associated genes in both PFAs and H3K27M DMGs with greatest variability in homeobox genes including HOXA2, HOXA4, and LHX2.." (PMID 36759899, 2023). "HOXA2 was upregulated in oral dysplasia but silenced during tumor progression." (PMID 35710803, 2022). "HOXA2 expression was upregulated in dysplasia but lost during the tumor progression." (PMID 35710803, 2022). "Thus, the results from three different methylation-detecting assays all indicated that HOXA2 was differentially hypermethylated in NPC tumor tissues." (PMID 24243817, 2013). "We then used quantitative (Q)-RT-PCR to evaluate the HOXA2 mRNA levels in the same NPC tumor tissues, and found that generally HOXA2 mRNA levels were reduced 5-~210-fold (compared with the corresponding adjacent normal tissues) in six out of the eight NPC tumors." (PMID 24243817, 2013). "Similarly, HOXA2 is part of the homeobox transcription factor family involved in cell differentiation during embryo development, acting as an oncogene in a variety of tumours." (PMID 38789628, 2024). "HOXA1, HOXA2, HOXA3, and HOXA10 had high expression in GBM tumor tissues compared to normal tissues." (PMID 37351805, 2023). "The percentage of methylation in the HOXA5, HOXA2, and HOXA6 genes in CRC were up to 67.62, 58.36, and 31.32%, respectively, and ranked first in CRC among all human tumor tissues." (PMID 31165042, 2019). "Because CyclinD1 inhibited Dicer expression by chromatin modifications, we further performed ChIP assays to determine whether altered CyclinD1 expression could also modulate the HP1α, H3K9me3 and SUV39H1 expression in the SOX2 and HOXA2 promoters in ICC and non-tumor HIBEpic cells." (PMID 31590696, 2019). "Therefore, the overall fold-change of the average methylation ratios of the tumor and non-tumor samples was 3.3 (***, p < 0.001), suggesting that the HOXA2 promoter is hypermethylated in NPC tumors." (PMID 24243817, 2013).
hematological neoplasms (1 paper, 2024). "Furthermore, in MSCs from all hematological neoplasms, we observed an overexpression of HOXA2 and HOXA3 as well as HOXB2-8 genes, which are crucial for hematopoietic cell fates and skeletal development." (PMID 38893194, 2024).
HOXA2 also shares sentences with these, for which no sentence is quoted: breast carcinoma (3 papers); nasopharyngeal carcinoma (3); non-small cell lung carcinoma (3); skin cancer (2); bladder cancer (1); colon adenocarcinoma (1); deafness (1); DiGeorge syndrome (1); gastric adenocarcinoma (1); gastric cancer (1); hand-foot-genital syndrome (1); Hearing impairment (1); hematopoietic cancers (1); hepatocellular carcinoma (1); immunodeficiency 32B (1); insulinoma (1); Intellectual disability (1); KBG syndrome (1); lung squamous cell carcinoma (1); mitochondrial disease (1); ovarian carcinoma (1); Parkinson disease (1); Rett syndrome (1); squamous cell carcinoma (1); systemic lupus erythematosus (1); testicular cancer (1); Weaver syndrome (1).